COL8A1 (collagen type VIII alpha 1 chain)
Diseases named in the same sentence as COL8A1 in open-access papers (continued):
Sharing a sentence is not in itself a finding about the gene and the disease.
macular edema (1 paper, 2023). "RPCs increased the expression of Col8a1, Col14a1, Col16a1 and Col18a1, among them, Col18a1 has been reported to be associated with macular edema, neovascularization, and retinal detachment in DR26." (PMID 37670124, 2023).
malignant glioma (1 paper, 2022). A grade III or grade IV glioma arising from the central nervous system. "Of the 12 overexpressed genes, ABCC3, COL8A1, IBSP and PDPN are reportedly associated with GBM, while CTHRC1, PDLIM4 and MYL9 are associated with high-grade and malignant gliomas, respectively." (PMID 35456975, 2022).
meningioma (1 paper, 2017). A generally slow growing tumor attached to the dura mater. "For instance, COL8A1 was identified by microarray analysis to be down-regulated in meningiomas." (PMID 29073243, 2017).
mental disorder (1 paper, 2022). A disease that has its basis in the disruption of mental process. "Eight genes are implicated in viral (SEC14L1, JMJD6, SRSF2, TMPRSS2, MX1, MX2) or bacterial (COL8A1, SPIRE1) infections, seven genes (MFSD11, METTL23, CTTNBP2, BACE2, IMPA2, MPPE1 and GNAL) are involved in mental disorders and one gene (MGAT5B) is related to the Golgi complex." (PMID 35581286, 2022).
myopia (1 paper, 2016). "Taken together, our results and those obtained in other studies indicate the importance of COL8A1 in retinal angiogenesis, both in pathological myopia and AMD." (PMID 27643879, 2016). "After correcting for multiple testing none of the polymorphisms studied remained significantly associated with myopic CNV (p>0.05); however, analysis of the axial length between genotypes of rs13095226 revealed an important influence of COL8A1 in the development of CNV in high myopia." (PMID 27643879, 2016). "Furthermore we conducted a meta-analysis of COL8A1, CFI and LIPC genes SNPs (rs669676, rs10033900 and rs10468017) and found that only rs669676 of these SNPs were associated with high myopia neovascularization." (PMID 27643879, 2016).
nasopharyngeal carcinoma (1 paper, 2025). A carcinoma arising from the nasopharyngeal epithelium. "COL8A1 has been reported to enhance metastasis in nasopharyngeal carcinoma by inducing epithelial-mesenchymal transition (EMT) and angiogenesis." (PMID 41004487, 2025).
renal failure (1 paper, 2019). "In addition, variant alleles of CDH16 and COL8A1 genes in Schnauzers might be an important link in understanding the high incidence of renal failure in Miniature Schnauzers, which are considered to have a breed predisposition to renal diseases." (PMID 31842489, 2019).
systemic sclerosis (1 paper, 2025). A chronic disorder, possibly autoimmune, marked by excessive production of collagen which results in hardening and thickening of body tissues. "Also, the upregulation of COL4A4, COL8A1, and COL11A1 in systemic sclerosis fibroblasts was not nearly as strong as that observed in NL fibroblasts." (PMID 39989459, 2025).
tumor (38 papers, 2007 to 2025). "COL8A1 is a gene that encodes for a component of the extracellular matrix, which has been implicated in tumor resistance and proliferation." (PMID 40224214, 2025). "Our clinicopathological data clearly indicated that COL8A1 was associated with tumor pathological stage." (PMID 35280763, 2022). "Interestingly, we showed that low expression of COL8A1 in OPSCC tumours and CAFs was significantly associated with low risk of death (i.e., HPV-positive, non-smokers)." (PMID 31717573, 2019). "While our in vitro data support a functional role for COL8A1, in vivo studies using animal models are required to fully validate its impact on tumor growth, TME remodeling, and response to therapy in a more physiologically relevant context." (PMID 41451204, 2025). "The precise molecular mechanisms by which COL8A1, presumably an extracellular matrix protein, regulates intracellular signaling in tumor cells and communicates with immune cells remain to be elucidated." (PMID 41451204, 2025). "More importantly, our coculture experiment revealed a novel paracrine function of COL8A1: its expression in tumor cells enhances the migration of microglia." (PMID 41451204, 2025). "The suppression of tumor migration and proliferation by COL8A1 knockdown was validated by functional tests." (PMID 41451204, 2025). "In contrast, subtype C showed the poorest clinical prognosis, accompanied by upregulation of tumor-promoting pathways and adverse prognostic genes such as COL8A1." (PMID 41004487, 2025). "Transcriptome analysis further revealed that COL8A1 was highly expressed in tumor samples and stage III/IV, as well as closely correlated with shorter survival time, underscoring its highly malignant behavior, which was validated by clinical CRC samples." (PMID 39732719, 2024). "We also found significantly upregulated myCAF markers in gal 4–KD tumor CAFs, including Col12a1, Col8a1, Thbs2, and Igfbp3." (PMID 36478037, 2023). "SOSTDC1, TLR5, MT1G, and MUC6 were downregulated in locally advanced tumor tissue samples, whereas COL8A1 and THBS2 were upregulated (P<0.05)." (PMID 36969001, 2023). "Western blot analysis of tumor tissues showed that COL8A1 knockdown reduced IFIT1 and IFIT3 expression, as well as EGFR phosphorylation." (PMID 35280763, 2022). "As tumor progression and metastasis is a complex process involving cell motility, including cell invasion and migration, we next examined the effects of COL8A1 expression on NSCLC cell invasion using transwell assays." (PMID 35280763, 2022). "Further, COL8A1 expression can be used to segregate gastrointestinal stromal tumors into different tumor behavior groups." (PMID 35280763, 2022). "COL8A1 is a collagen type VIII protein, and upregulation of COL8A1 has been correlated with tumour cell proliferation and invasion." (PMID 35205121, 2022). "Subsequently, we verified the correlation between the expressions of Wnt2 and COL8A1 in 158 tumor tissues of COAD patients by immunohistochemical analysis (P = 0.017)." (PMID 32983993, 2020). "Second, COL8A1 plays important role in modulating migration, proliferation, and adhesion of tumor cells." (PMID 32818022, 2020). "However, by 48 h post‐transplantation, the fluorescence intensity in the COL8A1 knockdown group was significantly reduced compared to the NC group, demonstrating that COL8A1 knockdown effectively inhibited tumour cell proliferation within the zebrafish model." (PMID 40461943, 2025). "Furthermore, the precise molecular mechanisms, specifically, the receptors through which COL8A1 signals and the detailed downstream pathways it activates in both tumor and immune cells, are yet to be elucidated." (PMID 41451204, 2025). "Tumor mutation burden analysis indicated that in 433 STAD samples, 73 samples showed altered mutation frequencies in PRG signatures, with mutation rates of 4% for COL8A1, 3% for DDB1, 3% for PARP1, and 3% for ESR2." (PMID 41004487, 2025).
tumor (continued). "Examination of COL8A1 expression at the single-cell level revealed its predominant expression inneoplastic cells, with additional expression in OPCs and astrocytes, suggesting both tumor-intrinsic and stromal sources contribute to its levels in the TME." (PMID 41451204, 2025). "The CCK8 and subcutaneous xenograft mouse model displayed that Ipatasertib could reverse the contribution of COL8A1 to oxaliplatin resistance and remarkably reduce tumor volume and weight." (PMID 39732719, 2024). "A recent study found paracrine and autocrine COL8A1 could bind to ITGB1 promoting tumor progression and gemcitabine resistance in PAAD." (PMID 39732719, 2024). "COL8A1-silenced xenograft tumors grew significantly more slowly than those in the control group, with tumor volume and weight in COL8A1-silenced tumors lower than those expressing control shRNA, suggesting that knockdown of COL8A1 suppressed tumor growth capacity in vivo." (PMID 35280763, 2022). "To further investigate whether COL8A1-mediated tumor progression required IFIT1 and IFIT3 knockdown, we examined cell proliferation in COL8A1-overexpressing and IFIT1/IFIT3-silenced NSCLC cells." (PMID 35280763, 2022). "Increased COL8A1 expression is closely related to tumor cell proliferation and invasion." (PMID 30760317, 2019). "COL8A1 might involve in the proliferation, adherence and migration of diverse cells, and overexpressed COL8A1 is detected in several rapidly proliferating cells, such as epithelial cells and tumor cells." (PMID 30065754, 2018). "However, by 24 h, the COL8A1 knockdown group exhibited a significant reduction in tail fluorescence area compared to the NC group, suggesting that the knockdown of COL8A1 effectively curtailed tumour cell migration." (PMID 40461943, 2025). "The PI3K/AKT signaling pathway plays a key role in COL8A1-mediated EMT and tumor cell proliferation." (PMID 41004487, 2025). "In comparison to tumor vasculature in MVP and CT regions, SLIT3, COL8A1, LUM and POSTN showed enhanced spatial enrichment within the GBM hyperplastic region." (PMID 41366031, 2025). "COL8A1, a key component of type VIII collagen, plays a critical role in extracellular matrix remodelling and tumour microenvironment dynamics." (PMID 40461943, 2025). "The TCGA and GETx datasets indicated that COL1A1, COL3A1, COL5A2, COL8A1, COL10A1, and COL12A1 genes were expressed much higher in tumor tissues than in the normal ones." (PMID 36900272, 2023). "The scRNA-seq data showed that ITGA2 was mainly expressed in tumor cells, while its ligands COL1A1, COL1A2, COL8A1, FN1, and HSPG2 were expressed in fibroblasts and endothelial cells." (PMID 35719923, 2022). "ITGA2 interacted with COL1A1, COL1A2, COL8A1, FN1, and HSPG2, mediating the tumor cell–fibroblast and tumor cell–endothelial cell connection." (PMID 35719923, 2022). "The infiltration of macrophages, neutrophils, and dendritic cells are positively correlated with these COL8A1, COL10A1, CTHRC1, and FAP, suggesting the need for exploration of their roles in the tumor microenvironment of GC." (PMID 35910202, 2022). "The expression of COL8A1, COL10A1 and COL17A1 were found to be significantly elevated in many different tumor types 30-34 and they were all tumor-related genes." (PMID 33753985, 2021). "For instance, COL8A1, COL8A2, and COL21A1 were only detected in normal tissues whereas COL7A1 and MUC1 were exclusively identified in tumor samples." (PMID 34199725, 2021). "The Oncomine database was used in our analysis and the mRNA levels of COL8A1, TIMP2, and GPR124 were higher in tumor tissues compared with normal tissues." (PMID 32095347, 2020). "We further showed that COL8A1 and COL11A1 are expressed by some HNSCC cell lines and are expressed by both tumour cells and CAFs in HNSCC tissues." (PMID 31717573, 2019).
tumor (continued). "Of these probe sets, several genes encoding proteins involved in extracellular matrix (ECM)-tumor interaction and focal adhesion (COL6A3, COL8A1, CTHRC1, THBS2, COMP) were upregulated, whereas ITGA2gene with the same function was downregulated in tumor cells." (PMID 17389037, 2007). "In addition to IGFBP7, the remaining differential genes (SDC2, COL8A1, IFI27, and ALDH1A1) were related to tumor drug resistance in the intersection of drug resistance differential genes." (PMID 40224214, 2025). "Strikingly, examining the source of collagen gene expression (COL1A1, COL1A2, COL3A1, COL6A1, COL8A1, COL10A1) provided clarity that the majority of genes expressed in the tumor samples represent transcripts of the MSC-related component of the tissue microenvironment." (PMID 36940196, 2023). "COL8A1 was initially identified as a major class of collagen type VIII, expressed by cornea and vascular endothelial cells, in the 1980s and was then further characterized as a tumor suppressor in hepatocarcinoma cells." (PMID 35280763, 2022). "We showed that genes co-expressed with WISP1 may act as tumor promotors by regulating ECM organization, with the collagen members COL6A3, COL5A1, and COL8A1 being key genes in a majority of cancers." (PMID 32523603, 2020). "Interestingly, increased mRNA expression was already observed in normal tissue of tumor patients compared to healthy donors for THBS2, SPARC, LTBP2 as well as the collagens COL8A1 and COL12A1." (PMID 29176937, 2017). "This suggests that COL8A1 is not only a tumor-intrinsic aggressiveness factor but also an active modulator of the TME, potentially facilitating the recruitment of pro-tumorigenic microglia/macrophages to the tumor site, which in turn can foster angiogenesis, invasion, and immunosuppression." (PMID 41451204, 2025). "Given that CAFs are reported to be an important stromal component and are critically involved in tumor progression, we reclustered the CAFs and further categorized them into two main types: inflammatory CAFs (iCAFs; CFD, CKB, and DPT) and myoblastic CAFs (myCAFs; INHBA, SULF1, and COL8A1)." (PMID 36725337, 2023). "The expression of these three target genes is also positively correlated with the degree of immune cell infiltration in the gastric cancer tumor microenvironment, suggesting that NOX4, COL8A1 and CHST1 may be involved in the establishment of the tumor immune microenvironment." (PMID 33193668, 2020).
cancer (30 papers, 2018 to 2026). A tumor composed of atypical neoplastic, often pleomorphic cells that invade other tissues. "Through mutational profiling, we identified distinct somatic mutation patterns distinguishing COL8A1-high from COL8A1-low cancers." (PMID 41451204, 2025). "It is now evident that COL8A1 has important roles in various biological processes, and its dysregulation has been linked to various cancers, including hepatic carcinoma and hemangioma." (PMID 35280763, 2022). "A few bioinformatic studies have shown that COL8A1 is a hub gene associated with several cancers, but this requires further investigation." (PMID 33564686, 2021). "Serum concentrations of COL8A1 increases in disease associated with vascular remodeling and forming including cancer." (PMID 29740513, 2018). "Therefore, searching for KEGG pathways with DO analysis, we established that COL8A1, DEGs, and positively related CEGs are associated with various cancers." (PMID 32818022, 2020). "In addition to promoting angiogenesis via PI3K/AKT activation, THBS2-expressing cancer-associated fibroblasts have been identified as drivers of oxaliplatin resistance through the secretion of COL8A1, which activates PI3K/AKT signalling and induces epithelial–mesenchymal transition." (PMID 40860666, 2025). "In vitro and in vivo experiments showed that COL8A1 knockdown inhibited cancer cell growth, invasion, and metastasis while enhancing chemosensitivity." (PMID 40461943, 2025). "Inhibition of COL8A1 attenuated cancer progression and enhanced oxaliplatin sensitivity, highlighting the promising role of COL8A1 as a target for overcoming oxaliplatin resistance." (PMID 39732719, 2024). "COL8A1 was also proposed to promote the migration of certain cancer cells by mediating ECM-receptor interaction." (PMID 35910202, 2022). "The TIMER database was utilized to investigate the association between COL8A1, COL10A1, CTHRC1, and FAP, and immune cell infiltration, as immune cell levels correlate with the proliferation and progression of cancer cells." (PMID 35910202, 2022). "Based on the proteoglycans in cancer pathway, we found that genes positively related to COL8A1 participate in the VEGF and mTOR signaling pathways, which have been identified as targets of TNBC treatments." (PMID 32818022, 2020). "And the positively correlation between the infiltrating levels of macrophages and the expression of COL5A1, COL6A3, and COL8A1 were confirmed in diverse cancer types using CIBERSORT method." (PMID 32523603, 2020). "We also examined correlations between expression of COL6A3, COL5A1, and COL8A1 with M1 and M2 macrophages in the seven selected types of cancer." (PMID 32523603, 2020). "Genes co-expressed with WISP1 were mainly associated with extracellular matrix organization, with collagen members COL6A3, COL5A1, and COL8A1 being key genes correlated with macrophage infiltration and M2 polarization in pan-cancer." (PMID 32523603, 2020). "Intersected DEGs and CEGs positively related to COL8A1 were significantly clustered in the proteoglycans in cancer and ECM-receptor interaction pathways." (PMID 32818022, 2020). "Together, these results suggest that the collagen members COL6A3, COL5A1, and COL8A1 are key genes in the seven selected cancers, reflecting alterations in ECM organization." (PMID 32523603, 2020). "We next examined correlations between expression of the collagen members COL6A3, COL5A1, and COL8A1 and markers of macrophages in the seven selected cancer types in TIMER." (PMID 32523603, 2020). "COL8A1, initially identified as a primary component of type VIII collagen in corneal and vascular endothelial cells, has recently been implicated in the progression of various cancers." (PMID 40461943, 2025). "Recent research has shown that COL8A1 is dysregulated in a variety of cancers." (PMID 35774273, 2022). "Recently, limited studies demonstrate the de-regulation of COL8A1 in various cancers." (PMID 32818022, 2020).
cancer (continued). "Additionally, in vitro and in vivo experiments confirmed that COL8A1 contributed to cancer progression and resistance in CRC, which could be mitigated by ITGB1 knockdown or AKT inhibitor." (PMID 39732719, 2024). "The highest expression of genes encoding Col1a1-2, Col3a1, Col4a1, Col4a2, Col5a1, Col5a2, Col6a1, Col8a1, Col9a3, Col10a1, Col12a1, Col14a1, Col15a1, Col16a1, Col18a1, and Col28a1 were detected in untreated tumors, whose landscapes were dominated by Krt8+ cancer cells." (PMID 39372930, 2024). "Also, enhanced monocyte-macrophage trafficking and M2 polarization are correlated with expression of collagen members COL6A3, COL5A1, and COL8A1, which may orchestrate the cancer-promoting effects of WISP1." (PMID 32523603, 2020). "COL8A1 is highly expressed in OA tissues and, like COL10A1, is a myofibroblastic-specific marker in cancer." (PMID 39939916, 2025). "In the next step, a comparison analysis using the cancer genome atlas (TCGA) PCa datasets confirmed elevated CLDN7, COL8A1, and ITGA10 mRNA expression in PCa tissue samples." (PMID 38017134, 2024). "In this study, we showed that COL6A3, COL5A1, and COL8A1 most likely be effector molecules of WISP1 and were positively correlated with monocyte infiltration and M2 polarization in pan-cancer." (PMID 32523603, 2020). "In this current study, several CAFGs—VIM, ANXA1, HOPX, CALD1, and COL8A1—were confirmed highly expressed in TC cells, but not in those of other cancers (except ANXA1 in PDAC)." (PMID 41228323, 2025). "The genome-wide co-expression analyses showed that the expression levels of collagen genes (COL1A1, COL1A2, COL5A1, COL5A2, COL8A1 and COL8A2) and LincRNAs (Linc01614 and Linc01711) were significantly positively correlated with PODNL1 expressions in various cancers." (PMID 37504302, 2023). "Although the function of COL8A1 is not completely elucidated, its dysregulation in various cancers has led to a proposed role in NSCLC development and progression." (PMID 35280763, 2022). "COL6A3, COL8A1, CDH11, and CXCL12 were not expressed in either PDAC tissues or normal tissues, and BGN and THBS2 were overexpressed in both cancer and normal tissues." (PMID 33282565, 2020).
infection (2 papers, 2023 to 2025). The state of being infected such as from the introduction of a foreign agent such as serum, vaccine, antigenic substance or organism. "Genes involved in cell adhesion and structural components, including laminins (LAMA2), elastin (ELN), and collagens (COL16A1, COL13A1, COL8A1) were significantly downregulated at 24 hours post-infection (hpi) in both variants." (PMID 41200555, 2025).
cardiovascular disease (1 paper, 2025). "Of particular relevance to PVAT remodeling during cardiovascular disease is the observed expression of Col8a1 and Col8a2 and their downregulation during adipogenesis." (PMID 40277904, 2025).